RN7SKP109 (RN7SK pseudogene 109)
Gene: Miscellaneous RNA gene on chromosome 19 (55,737,285 to 55,737,600, forward strand). Ensembl gene ENSG00000222524.
Homologues: Orthologues: chimpanzee 7SK (99% identical), guinea pig 7SK (58% identical), guinea pig 7SK (57% identical), guinea pig 7SK (53% identical), guinea pig 7SK (51% identical), guinea pig 7SK (50% identical), mouse Gm56312 (45% identical). Paralogues in human: RN7SKP180 (67% identical), 7SK (67% identical), RN7SKP79 (66% identical), RN7SKP217 (65% identical), RN7SKP78 (65% identical), RN7SKP128 (64% identical), RN7SKP176 (64% identical), RN7SKP189 (64% identical), RN7SKP47 (64% identical), RN7SKP127 (64% identical), RN7SKP160 (64% identical), RN7SKP9 (64% identical), and 284 more.